EPO (erythropoietin)
Diseases named in the same sentence as EPO in open-access papers (continued):
Sharing a sentence is not in itself a finding about the gene and the disease.
anemia (continued). "Major causes of anemia in CKD patients include deficiencies in erythropoietin and iron." (PMID 37602095, 2023). "Thus, TNFα, IL-1β, IL-6 and IFN-γ seem to be responsible for impaired EPO synthesis in the development of anemia associated with inflammation." (PMID 37240288, 2023). "According to previous studies, blood marrow deficiency or malnutrition, bleeding from tumor sites, metastasis, catabolism in tumor patients, and relative deficiency of erythropoietin may be involved in the pathogenesis of anemia." (PMID 37777739, 2023). "The possible underlying mechanisms include abnormal red blood cells, oxidative stress, and sympathetic denervation of the kidney resulting from hyperglycemia, which promote hypoxia and erythropoietin stress that eventually may cause anemia." (PMID 37163539, 2023). "Ensuring that vitamin D levels remain above this threshold would possibly help athletes prevent a decline in iron and hemoglobin levels because of training, especially considering the possible interaction between vitamin D and EPO, and the co-occurrence of vitamin D deficiency and anemia." (PMID 37895389, 2023). "The first target for the treatment of inflammatory anemia is to treat the underlaying disease; if anemia is severe, blood transfusion or treatment by erythropoietin-stimulating agents may be necessary." (PMID 37298597, 2023). "Therefore, this study assessed the production of anti-EPO antibodies and their association with anaemia in P. falciparum-infected pregnant women." (PMID 36989322, 2023). "BUN/Cr > 25 may help guide practitioners to identify patients with normal-high reported hemoglobin levels but underlying anemia who may need further iron or erythropoietin treatment prior to surgery." (PMID 36611176, 2023). "However, compared with patients with iron-deficiency anemia, EPO production is reduced in patients with cancer-induced anemia." (PMID 37208766, 2023). "Such inflammatory cytokines cause anemia by reducing the production of erythropoietin." (PMID 37102031, 2023). "One potential study design could involve comparing the EPO levels of anemic patients to those of younger patients with uncomplicated iron deficiency and the same degree of anemia." (PMID 37240288, 2023). "Deficiency of erythropoietin and deficiency of iron are the two major reasons for anemia in CKD." (PMID 36983703, 2023). "The development of anemia in patients with decreased renal function is thought to be related to other comorbidities such as diabetes, where the EPO deficiency is a consequence of interstitial fibrosis, diabetic nephropathy, or glycation of the EPO receptor due to hyperglycemic status." (PMID 37374094, 2023). "Studies have found that chronic kidney disease patients are more prone to blood loss anemia necessitating blood transfusion due to multiple factors including preoperative anemia of chronic disease, low erythropoietin level, and perioperative higher bleeding risk due to uremic effect on the platelet." (PMID 37789382, 2023). "Hence, functional erythropoietin deficiency and/ or erythropoietin resistance in DM are the plausible reason for developing anemia." (PMID 37163539, 2023). "Based on the protective role exerted by roxadustat in anemia, roxadustat has been proven to be beneficial in anemia patients with lower-risk myelodysplastic syndrome who has low EPO level (<400 m IU/mL) and receive 1–4 RBC units infusion per eight weeks (NCT03263091)." (PMID 36724056, 2023). "Reduced erythropoietin production, long-lasting inflammation, obesity, hormone deficiency or resistance, or disturbed iron supply for erythropoiesis are the main triggers of anemia." (PMID 37760862, 2023). "Inflammatory responses to surgery may create a relative iron- and erythropoietin-deficient postoperative anemia state that may delay patient recovery from surgery." (PMID 37464433, 2023).
anemia (continued). "Iron deficiency and anemia in pregnancy and the puerperium should be treated according to a staged regimen, administering either iron alone or in combination with human recombinant erythropoietin in selected patients." (PMID 37435001, 2023). "Erythropoietin and iron deficiencies are the major causes to develop anemia in CKD patients." (PMID 37602095, 2023). "The principal cause of CKD-associated anemia is interrelated to the relative deficiency of EPO." (PMID 38022248, 2023). "This reduction in GalnT3 mRNA may contribute to an increase in FGF23 cleavage under conditions characterized by elevated erythropoietin, such as iron deficiency anemia, inflammation, or exogenous treatment with synthetic erythropoietin." (PMID 37681408, 2023). "Loss of EPO or EPOR causes death in utero due to severe anemia." (PMID 36895793, 2023). "As has been noticed in Itai-Itai disease, Cd also seems to induce anemia, due to the suppression of erythropoietin production; this mechanism, linked to the suppression of iron transport in the duodenum, may cause iron-deficient anemia." (PMID 36671421, 2022). "Additionally, anemia and iron deficiency are strong inducers of EPO, and transgenic mice overexpressing EPO were found to have elevated FGF23." (PMID 35656701, 2022). "In addition, when there are both HF and a decline in renal function, the kidney reduces EPO production and increases urinary loss of serum EPO and transferrin, resulting in anemia's progression." (PMID 35581275, 2022). "The risk of anemia in individuals with diabetes may be due to inadequate responsiveness to EPO, which can be caused by decreased EPO concentration, EPO functional defect and/or EPO resistance." (PMID 35414128, 2022). "The cause of tumor-related anemia may depend on the dysfunction of iron metabolism, inadequate production of erythropoietin, reduced number of erythroid progenitor cells in the bone marrow, and the production of inflammatory cytokines." (PMID 36464677, 2022). "Multiple factors contribute to the onset of anemia: tumoral hemorrhage, hemolysis, hypersplenism, renal failure associated with decreased erythropoietin production, bone marrow failure due to metastasis, myelodysplastic syndrome, or chemoradiotherapy-associated myelotoxicity." (PMID 36011082, 2022). "Thus, inability to increase erythropoietin concentration in response to decreased Hgb is considered to be the main cause of anemia in DF." (PMID 36557068, 2022). "The primary cause of this anaemia is a deficiency of erythropoietin (EPO)." (PMID 35892014, 2022). "Our results are consistent with the hypothesis that PHIs are not likely to increase CVD risk or CVD risk factors in treating anemia of CKD when increasing circulating EPO levels within the physiological range." (PMID 36055212, 2022). "Thus, overall, vadadustat had beneficial effects on three aspects of erythropoiesis in patients with anemia associated with CKD: increased endogenous EPO production, improved iron availability to erythroid cells, and increased reticulocytes in the circulation." (PMID 35751858, 2022). "In hemodialyzed patients, it might therefore be assumed that anemia is not only due to deficiency of erythropoietin produced and secreted in the kidneys; the mechanism is more complex." (PMID 35566552, 2022). "Anemia in HF patients is associated with impaired renal function, potentially causing impaired erythropoietin production, and patients with HF often have systemic inflammation, which may lead to bone marrow suppression." (PMID 34611778, 2022). "Whether there is a need to further refine treatment strategies for patients having anaemia of chronic inflammation with iron deficiency, such as using recombinant erythropoietin, requires further study in this study population." (PMID 35771891, 2022).
anemia (continued). "The prevalence of anaemia in patients with cancer is reported to be approximately 40% due to nutritional deficiency, chronic disease, blunted response to erythropoietin, bone marrow suppression either due to cancerous cells or as a side effect of chemotherapy/radiotherapy, and other causes." (PMID 35820820, 2022). "CKD anemia is usually caused by multiple factors, including a decreased red blood corpuscle (RBCs), an increased level of chronic inflammation-associated hepcidin that sequesters iron stores, and hypo-responsiveness induced by uremia to erythropoietin (EPO)." (PMID 35628849, 2022). "The absolute or relative deficiency of EPO is the most important factor leading to anemia." (PMID 36225579, 2022). "The pathophysiology of anemia in heart failure patients is multi-factorial and has been linked to the presence of hematinic deficiencies, specifically iron deficiency (ID) anemia, chronic inflammation, or impaired erythropoietin levels." (PMID 36017290, 2022). "The literature data showed that OS could be marked as a significant risk factor for the development of anemia in patients treated by regular HD due to EPO resistance." (PMID 35464768, 2022). "Erythropoietin (EPO) deficiency is one of the factors that causes anaemia in patients with CKD." (PMID 35743505, 2022). "Already in the early 1990’s, it was hypothesized that anemias associated with low serum EPO levels might respond to treatment with recombinant EPO." (PMID 36211426, 2022). "Anemia of inflammation (AI) is caused by disturbances of iron metabolism resulting in iron retention within macrophages, a reduced erythrocyte half-life, and cytokine mediated inhibition of erythropoietin function and erythroid progenitor cell differentiation." (PMID 34835988, 2021). "Nonetheless, increased JAK2 activity may also be caused by high levels of EPO caused by anemia and chronic hypoxia, a state observed in β-thalassemia and cancer." (PMID 33669537, 2021). "The surgeon prescribed EPO therapy in patients with anaemia at high risk of undergoing transfusion." (PMID 34838063, 2021). "The use of multivitamin injections for vitamin supplementation and erythropoietin injections for neonatal anemia were associated with a higher likelihood of polysorbate 80 use, responsible for 59 (51.3%) and 37 (32.2%) of 115 polysorbate 80-containing prescriptions, respectively." (PMID 34193299, 2021). "The main cause of EPC expansion is the increase in EPO concentrations in response to anemia." (PMID 33669537, 2021). "Although the mechanism‐underlying anemia in COVID‐19 is unknown, a possible explanation resides in the finding that pro‐inflammatory cytokines inhibit erythropoietin‐induced erythropoiesis." (PMID 33190411, 2021). "Hence, following blood loss or during chronic anemia, hypoxic conditions induce increased EPO levels, which stimulate ERFE expression by erythroblasts and consequently downregulate hepcidin production to provide extra iron supply to support erythropoiesis." (PMID 33672223, 2021). "Anemia of CKD may also be due to erythropoietin (EPO) resistance, clinically associated with inflammation." (PMID 33737665, 2021). "These diversely unique properties of EPO, taken together with its clinical use to treat anemias associated with chronic renal failure and other blood disorders, make it a valuable biologic agent in regenerative medicine for the treatment/cure of tissue de-regeneration disorders." (PMID 34440909, 2021). "The major cause of anemia in the EPO group was CKD and iron deficiency anemia." (PMID 34831360, 2021). "Since inflammatory cytokines underlie the development of anemia and resistance to erythropoietin treatment, anti-inflammatory treatment could be beneficial in the treatment of anemia and the prevention of psoriasis in CKD patients." (PMID 34285267, 2021).
anemia (continued). "These outcomes may reflect the normal erythropoietic activity in bone marrow and probably exclude the decreased erythropoietin response and common malnutrition as the leading causes of anemia in solid cancer patients at diagnosis." (PMID 33507998, 2021). "The reported prevalence of anemia in the elderly is 2.9%–51% and correlates with advanced age and multiple related conditions, including iron deficiency, inflammatory conditions, malignancy, and low serum erythropoietin." (PMID 34250431, 2021). "In addition, anemia due to ACEIs and ARBs has been associated with decreased erythropoietin production as a result of increased renal plasma flow and increased oxygen delivery." (PMID 34519192, 2021). "First, in iron-deficient anemia, a high dosage of recombinant human erythropoietin could boost erythropoiesis to a sufficient degree in a dose-dependent manner." (PMID 34436045, 2021). "Neutralizing antibodies can also adversely affect other organs, as demonstrated by recombinant human erythropoietin leading to anemia resulting from antibody-dependent immune responses, which destroy both extrinsic and intrinsic erythropoietin, thus causing abnormal RBC development and production." (PMID 34683950, 2021). "Although EPO deficiency is a common predictor of anemia, some studies show that liver and macrophage synthesis of EPO is observed, moreover this could be an attempt to compensate for reduced EPO synthesis in the kidney." (PMID 34356833, 2021). "Interestingly, EPO was originally seen as a potential treatment for sepsis-associated anemia because there is low EPO in critically ill patients but high EPO in sepsis." (PMID 34831360, 2021). "Further studies are needed to determine whether the treatment with EPO and iron sulfate is more effective in treating iron deficiency and anemia when combined with exercise training in patients with ESRD." (PMID 34579127, 2021). "Moreover, the decrease in the ability to synthesize erythropoietin due to kidney disfunction causes the appearance of anemia." (PMID 34360098, 2021). "Kidney disease can cause anemia due to reduced levels of erythropoietin levels." (PMID 34715799, 2021). "We deduce that early recognition of the problem will allow for timely introduction of adequate causative treatments such as supplementation of vitamins, iron, or erythropoietin, amelioration of comorbidities that are commonly associated with anemia, and/or allogeneic blood transfusions." (PMID 34663297, 2021). "Although there is no definitive explanation for this phenomena, it may be that the hormonal effects on erythropoietin activity and the higher pre- and postnatal growth rate may play a role in the increased susceptibility of male children to anemia." (PMID 34736513, 2021). "Anemia is a frequently observed complication of nephrotic syndrome but occurs as a result of urinary loss of erythrogenic factors such as iron, transferrin and erythropoietin." (PMID 34203913, 2021). "Moreover, anemia caused by a relative deficiency of erythropoietin is a common complication in ESKD patients." (PMID 34383773, 2021). "Furthermore, chronic kidney disease, which impairs the kidneys’ ability to produce sufficient erythropoietin, was found to be one of the leading causes of anemia from the sixth decade of life onwards." (PMID 34736513, 2021). "The primary cause of anemia is a reduction in EPO synthesis due to loss of renal functional mass." (PMID 34873402, 2021). "Despite the lack of high-level evidence, the consensus for patient blood management recommends early management anemia before cardiac surgery, including preoperative iron supplementation for iron-deficiency anemia and consideration of erythropoietin in patients with specific conditions." (PMID 35127586, 2021). "The worsening of anemia with the progression of the IRIS stage may be related to several mechanisms beside EPO deficiency." (PMID 34209294, 2021). "Chronic kidney diseases lead to anemia due to EPO deficiency." (PMID 34692308, 2021).
anemia (continued). "By contrast, remodeled bone microarchitecture, inhibited erythropoietin production, and disordered iron homeostasis are speculated to account for anemia‐associated degenerative bone disorders upon heavy metal exposure." (PMID 33042736, 2020). "The causal mechanism behind anaemia in the preoperative setting might require treatment with concurrent erythropoietin as seen in cardiac surgery." (PMID 32896294, 2020). "Anemia in ESRD patients has also been demonstrated to be caused mainly by insufficient synthesis of erythropoietin (EPO) combined with erythropoietin resistance as well as a higher erythropoietin demand." (PMID 32318578, 2020). "Anemia is a frequent finding in individuals undergoing hemodialysis, mainly due to the decrease in EPO concentrations, but also due to the impaired response to EPO, and an increase in serum Mg2+ seems to decrease the risk of a lesser response to EPO." (PMID 32992944, 2020). "This could be through the deleterious effect of blood transfusions, or the endogenous production of erythropoietin in response to anaemia, manifesting clinically as increased risk of stroke, MI, and mortality among STEMI patients." (PMID 32403442, 2020). "Similarly, in the setting of CKD and ESRD, correction of anemia with recombinant EPO led an increased risk of cardiovascular morbidity and death." (PMID 32512806, 2020). "Anemia caused by a reduction in renal erythropoietin (EPO), as a consequence of CKD may also affect cardiac function." (PMID 33135539, 2020). "The pathophysiology of anemia related to HF is caused by many factors and includes renal imbalance and reduced erythropoietin production, increased production of proinflammatory cytokines like interleukins and tumor necrosis factor, increase in plasma volume, and lower production of erythropoietin." (PMID 32676505, 2020). "But to date, the current indication for EPO in cancer is mainly anemia caused by chemotherapy." (PMID 32684930, 2020). "HIV may cause anaemia directly through an inhibitory effect of the HIV-virus on the erythropoietin progenitor cells in the bone marrow, or indirectly through opportunistic infections and/or inflammation causing anaemia." (PMID 32097440, 2020). "EPO levels and/or anemia status and its association with mid-term mortality were assessed." (PMID 33330669, 2020). "A number of studies have reported a high prevalence of zinc deficiency, and zinc supplementation ameliorates several clinical problems related to zinc deficiency, such as erythropoietin resistant anemia, dysgeusia, and hypogonadism, in patients undergoing hemodialysis." (PMID 33043035, 2020). "Human recombinant erythropoietin (rEPO) has been widely used to treat anemia associated with CKD." (PMID 32184703, 2020). "Indeed, our experiments indicated the possibility that Nrf2 activation mitigates anemia, which is caused by impaired production of the erythroid growth factor erythropoietin from injured kidneys, and moderates organ damage worsened by anemic hypoxia." (PMID 32331329, 2020). "Chronic kidney disease was diagnosed in at least two of these elephants (AE1, AE3) that may have caused impaired erythropoietin production, possibly contributing to the mild anemia in these elephants." (PMID 33195633, 2020). "The understanding of underlying mechanisms of anemia in CKD is important due to the fact that in some patients erythropoietin stimulating agents (ESA) treatment might be least ineffective or even deleterious." (PMID 31979104, 2020). "In light of this, we performed a retrospective cohort study in order to do a cost-effectiveness analysis from the payer perspective to estimate the potential impact of using two treatment strategies for anemia associated with CKD: short-acting erythropoietin: epoetin-beta three times weekly vs." (PMID 33415047, 2020).